ALB (albumin)
Diseases named in the same sentence as ALB in open-access papers (continued):
Sharing a sentence is not in itself a finding about the gene and the disease.
bone metastasis (21 papers, 2009 to 2026). Transfer of a neoplasm from its primary site to bones. "Univariate analysis identified several clinical and laboratory parameters significantly associated with reduced OS, including ECOG PS ≥ 1, bone metastasis, low serum albumin, and low LMR." (PMID 40869718, 2025). "In univariate analysis, serum albumin level and the existence of bone metastasis, all with p-values <0.05, were selected as candidate risk factors." (PMID 29183294, 2017). "A multivariate analysis showed that low serum albumin level and the existence of bone metastasis were significantly associated with the early termination of chemotherapy (p = 0.0493 and 0.0174, respectively)." (PMID 29183294, 2017). "On univariate analysis, four variables demonstrated a statistically significant association with survival: nutritional status, bone metastasis, corrected serum calcium and serum albumin (p<0.05 for all)." (PMID 25774530, 2015). "On multivariate analysis, five variables demonstrated statistically significant associations with survival: hospital location, age, bone metastasis, serum albumin and corrected serum calcium (p<0.05 for all)." (PMID 25774530, 2015). "Five variables demonstrated statistically significant associations with survival: CTCA hospital, age, bone metastasis, serum albumin and corrected serum calcium." (PMID 25774530, 2015). "Key factors included a BMI <18.5 or ≥23, presence of bone metastasis, neutrophil-to-lymphocyte ratio ≥ 5, albumin-to-globulin ratio < 1, and mean pulmonary artery diameter ≥ 29 mm." (PMID 40805260, 2025). "Significant predictors of mortality included body mass index <18.5 or ≥23, bone metastasis, neutrophil-to-lymphocyte ratio ≥ 5, albumin-to-globulin ratio < 1, and mean pulmonary artery diameter ≥ 29 mm." (PMID 40805260, 2025). "The significant prognostic factors in univariable analysis for OS included sex, performance status, level of serum albumin, serum neutrophil-to-lymphocyte ratio, clinical T and N stage, liver metastasis, bone metastasis, and clinical complete response." (PMID 38001681, 2023). "Logical and clinical relationships were a priori established to define and associate the considered variables including cancer type, body mass index (BMI), bone metastasis, serum albumin, nutritional support, breakthrough cancer pain (BTcP), and radiotherapy." (PMID 36292299, 2022). "In univariate analysis, serum albumin level, number of cycles, the existence of bone metastasis, and the existence of adrenal gland metastasis, all with p-values <0.05, were selected as candidate factors." (PMID 29183294, 2017). "Patients who did not undergo gastrectomy and those with Borrmann type 4 disease, bone metastasis, low albumin levels, or elevated alkaline phosphatase (ALP) levels exhibited poorer PFS." (PMID 27802183, 2017). "When comparing the clinical and laboratory data between two groups, the incidence of bone metastasis was higher and serum albumin levels were lower in the early termination group than in the continuous treatment group." (PMID 29183294, 2017). "They reported that decreased albumin, increased alkaline phosphatase, bone metastasis, or ascites adversely affected the survival rate." (PMID 25889520, 2015). "Univariate analysis revealed that factors associated with inferior OS included male, age ≥ 62 years old, current or former smoker, liver metastasis, bone metastasis, low ChE at baseline (p = 0.004), a reduction level of ChE (p < 0.001), low ALB, high CRP and high SAA." (PMID 38730286, 2024). "Mucinous or non-mucinous histology, ECOG score, bone metastasis, ascites, hemoglobin concentration, serum albumin level, lactate dehydrogenase level, carcinoembryonic antigen level, and chemotherapy were finally incorporated into prognostic nomogram." (PMID 34895168, 2021).
bone metastasis (continued). "Our previous retrospective study in 1455 AGC patients have revealed that poor prognostic factors were no previous gastrectomy, low albumin, high alkaline phosphatase, bone metastasis, the presence of ascites, and a poor performance status." (PMID 19358705, 2009). "These variables were as follows: Mucinous or non-mucinous histology, ECOG score, bone metastasis, peritoneal metastasis or malignant ascites, HGB concentration, ALB level, LDH level, CEA level, and palliative chemotherapy." (PMID 34895168, 2021). "The following factors were significantly associated with a shorter OS: ECOG performance status ≥ 2, no gastrectomy, Borrmann type 4 disease, bone metastasis, lung metastasis, elevated ALP levels, and low albumin levels." (PMID 27802183, 2017).
Hematuria (21 papers, 2015 to 2025). The presence of blood in the urine. "After multivariable logistic regression analysis, age, serum albumin, serum IgA, serum immunoglobulin G, estimated glomerular filtration rate, serum IgA/C3 ratio, and hematuria were found to be independently associated with the presence of IgAN." (PMID 35585099, 2022). "On multivariable analysis, higher systolic blood pressure, higher serum albumin, lower eGFR, and presence of hematuria associated with FSGS." (PMID 33510182, 2021). "Univariate logistic regression analysis revealed that age, systolic blood pressure, serum albumin, serum total cholesterol, serum creatinine (log-transformation), eGFR and presence of urinary red blood cells and hematuria were significantly associated with a diagnosis of FSGS." (PMID 33510182, 2021). "We then stratified patients according to the composite of TA-hematuria (high vs. low) and TA-serum albumin (high vs. low)." (PMID 36431262, 2022). "The persistent hematuria group had a higher percentage of patients with macroscopic hematuria, lower levels of hemoglobin and TA-serum albumin, and more severe renal pathologic lesions." (PMID 36431262, 2022). "Microalbuminuria, hematuria, ALB reduction, elevated CYS-C, and CA-125 are predictive factors for the development of AKI in patients with PTB during anti-TB treatments." (PMID 35373713, 2022). "At the latest follow-up examination, BUN, SCr, serum UA and albumin levels, proteinuria severity, and hematuria severity were similar in the two groups." (PMID 28904360, 2017). "For indicating morbidity caused by urogenital schistosomiasis, rapid tests such as reagent strips showing the grade of hematuria, and detecting proteinuria and leukocyturia or urine albumin and creatinine have clear advantages." (PMID 25973845, 2015). "The protective effects of MOF-VVPP at the glomerular level can be suggested from the tendency to decrease proteinuria and the albumin/creatinine ratio, as well as from the significant reduction of the number of cases of exercise-related hematuria compared to the placebo." (PMID 32492913, 2020). "The results of the univariate logistic regression analysis indicated that age, gender, clinical classification, hematuria severity, urine protein severity, blood WBC levels, ALB levels, Cys-C levels, APTT, and PT may be associated with the development of crescents." (PMID 40870466, 2025). "The serum uric acid, triglyceride and 24-h urine protein were higher in patients with non-isolated hematuria IgAN (p < 0.05), while albumin was lower [(40.8 ± 5.8) g/L vs. (32.9 ± 8.9) g/L, p < 0.01]." (PMID 37089927, 2023). "At the final follow-up, the persistent hematuria group had a significantly lower TA-serum albumin level (39.70 [IQR: 36.03, 41.84] vs. 41.68 [IQR: 37.41, 43.72] g/L, p = 0.022), compared with the hematuria remission group, which was still significant in females." (PMID 36431262, 2022).
Kawasaki disease (21 papers, 2013 to 2025). A rare inflammatory disease characterized by an acute febrile, systemic, self-limiting, medium-vessel vasculitis primarily affecting children. "Some systems assessing the risk of IVIGresistance in Kawasaki disease use albumin levels below 3.5 g/dL as the referencestandard." (PMID 39618856, 2024). "LASSO identified haemoglobin, percentage of neutrophils, C-reactive protein level, platelet count, serum albumin, serum sodium, serum alkaline phosphatase, coronary artery damage, and complete Kawasaki disease as risk factors for IVIG resistance." (PMID 35099338, 2022). "LASSO regression reidentified haemoglobin level, percentage of neutrophils, C-reactive protein, serum albumin, and serum alkaline phosphatase levels, and complete Kawasaki disease as risk factors for IVIG resistance." (PMID 35099338, 2022). "Male sex, older, higher platelet count, higher CRP level, and lower albumin level in the initial phase of Kawasaki disease were strong risk factors of cardiac lesions." (PMID 25716055, 2015). "High erythrocyte sedimentation rate, high platelet count, low hematocrit, low albumin levels, and refractory Kawasaki disease showed significant association with coronary artery involvement." (PMID 26835677, 2013). "Extremes of age, longer duration of fever, higher white blood cell count, lower or higher platelet count, higher C-reactive protein, low hematocrit, and low serum albumin have been reported to be associated with coronary artery involvement in Kawasaki disease." (PMID 26835677, 2013). "In children with KD, serumalbumin increases permeability and leakage of fluid during the acute stage.Previous research has shown that acute stage albumin levels are decreased inintensive Kawasaki disease." (PMID 39618856, 2024). "Stratified analysis of the effects of ALB levels on CALs progression among Kawasaki disease patients." (PMID 36186633, 2022). "these variables were haemoglobin, percentage of neutrophils, platelet count, CRP, serum albumin, serum sodium, serum alkaline phosphatase, coronary artery damage, and incomplete Kawasaki disease." (PMID 35099338, 2022). "Albumin (ALB) level is closely associated with the occurrence of intravenous immunoglobulin (IVIG) resistance and coronary artery lesions (CALs) in Kawasaki disease (KD)." (PMID 36186633, 2022). "Clinicians should consider sex, age, platelet count, albumin levels, and CRP levels when assessing risk of cardiac lesions in the initial phase of Kawasaki disease." (PMID 25716055, 2015). "Clinicians should consider male sex, older age, higher platelet count, lower albumin levels, and higher CRP levels when assessing risk of cardiac lesions in the initial phase of Kawasaki disease." (PMID 25716055, 2015). "In the present study, patients with Kawasaki disease and coronary artery involvement had higher erythrocyte sedimentation rate and platelet count and lower hematocrit and albumin levels." (PMID 26835677, 2013). "Independent effect of ALB level on CALs progression among Kawasaki disease patients." (PMID 36186633, 2022). "Plasma exchange with 5% albumin was effective for refractory Kawasaki disease." (PMID 29541684, 2018). "We have reviewed four cases of Kawasaki disease treated with plasma exchange with 5% albumin in electrolyte-balanced solution, according to the recommended guidelines for Kawasaki disease in the intensive care unit, as their responses to intravenous immunoglobulin therapy were poor." (PMID 29541684, 2018). "Our study used common laboratory indicators WBC, MO, ESR, ALT, ALB, CPR, CLR to construct a prediction model of Kawasaki disease." (PMID 38434730, 2024). "Compared with the IVIG-sensitive group, the duration of hospitalization, ALT, AST, GLB, r-GT, IgG, PCT, and ESR were elevated and RBC, HGB, ALB, A/G, and CK were significantly lower in the IVIG-resistant Kawasaki disease group (P < 0.05)." (PMID 38114939, 2023).
Kawasaki disease (continued). "In the present study, low haemoglobin, low serum albumin, high percentage of neutrophils, high CRP, high AST, the presence of coronary artery lesions, and complete Kawasaki disease were predictors of IVIG resistance." (PMID 35099338, 2022). "RBC, HB, CK, CK-MB, ALB, A/G, LC3II, ATG16L1 were positively correlated with BECN1; the incidence of IVIG-resistant Kawasaki disease, length of stay, lymph node enlargement, perianal desquamation, CAL, IL-4, IL-6, CRP, PCT, SF, CD3 + CD4 + T, and r-GT were negatively correlated with BECN1." (PMID 38114939, 2023).
multiple sclerosis (21 papers, 2016 to 2025). A progressive autoimmune disorder affecting the central nervous system resulting in demyelination. "In multiple sclerosis (MS), the κFLC index calculated from cerebrospinal fluid (CSF) and serum FLC/albumin ratios is the validated diagnostic biomarker." (PMID 40806736, 2025). "Levels of CSF protein, consisting mostly of albumin, are about 8 μM in infants, about 15 μM in adults, and much higher following infarct or in conditions such as neuromyelitis optica and multiple sclerosis." (PMID 38868201, 2024). "It has also been reported that serum ALB level is an important factor affecting the degree of disability in patients with multiple sclerosis." (PMID 37821922, 2023). "A cohort study of multiple sclerosis found that cerebrospinal fluid/serum albumin is an independent variable for the prognostication of multiple sclerosis." (PMID 36817098, 2022). "The category of Inflammation was widely distributed across the Reiber diagram; however, the subgroup of cases suffering from multiple sclerosis showed the tendency for higher IgG CSF levels while having low albumin CSF levels (sensitivity = 75%, specificity among inflammations = 100%)." (PMID 40112826, 2025). "For example, in a study of CSF characteristics in pediatric-onset multiple sclerosis, 87% of children with early-onset multiple sclerosis had a normal albumin quotient (CSF albumin/serum albumin level) and relatively broad range of total CSF protein (100–720 mg/L)." (PMID 39224487, 2024). "Similarly, normal values have been reported in adult multiple sclerosis with an elevated albumin quotient in only 12–23% of cases." (PMID 39224487, 2024). "In addition, ALB has been found to be a predictor of the diagnosis of multiple sclerosis and in distinguishing progressive multiple sclerosis." (PMID 37821922, 2023). "However, cohorts without hypoalbumemia have also been reported and the role of albumin in multiple sclerosis is controversially discussed in the literature." (PMID 35842435, 2022). "The main aim of this study was to assess the diagnostic accuracy (AUC) of the kappa index (CSF/serum KFLC divided by the CSF/serum albumin ratio) compared to CSF oligoclonal IgG bands (OCB) in predicting Multiple Sclerosis (MS) or a central nervous system infectious/inflammatory disorder (CNSID)." (PMID 33096861, 2020).
Proteinuria (21 papers, 2009 to 2025). Increased levels of protein in the urine. "Our results of the negative correlation between serum and urine albumin is consistent with another study among diabetic patients showing that serum albumin levels were negatively associated with macroalbuminuria and nephrotic proteinuria." (PMID 35807807, 2022). "Proteinuria is strongly associated with kidney disease progression but the mechanisms underlying podocyte handling of serum proteins such as albumin and IgG remain to be elucidated." (PMID 30811433, 2019). "Proteinuria is the most common manifestation of kidney disease, accumulating evidence showed that excessive albumin exposure elicited tubular cell injury and interstitial inflammation which determines the prognosis of renal disease." (PMID 32641688, 2020). "Ongoing Phase III trials, such as ZENITH High-Proteinuria,aim to determine whether the decrease in albumin levels in response to zibotentanand dapagliflozin will have a lasting effect on kidney protection." (PMID 41524047, 2025). "Heterogeneity was found between studies (Proteinuria: I2 = 56%, Serum albumin: I2 = 75%)." (PMID 39664513, 2024). "Glomerular proteinuria leads to substantial amounts of plasma proteins being filtered into the tubular fluid, in particular albumin, which may reduce megalin‐mediated uptake of freely filtered proteins through competitive inhibition." (PMID 38124617, 2024). "Abnormal urine albumin (Albuminuria and Proteinuria) was present in all patients with CVD." (PMID 30064397, 2018). "Proteinuria, and particularly albuminuria, are characteristic in both PGN and NPGN, leading to a decreased concentration of albumin in serum." (PMID 32079183, 2020). "Proteinuria is a major AE of bevacizumab and may be the reason for the albumin reduction; however, there was no apparent difference in the rates of proteinuria between the two studies." (PMID 37537956, 2023). "Therefore, we divided diabetic population based on urine albumin-to-creatinine ratio (ACR) into Proteinuria (ACR>30 mg/g creatinine) and Non-Proteinuria (ACR<30 mg/g creatinine) groups." (PMID 23544132, 2013).
carotid atherosclerosis (20 papers, 2014 to 2025). A thickening and loss of elasticity of the walls of carotid arteries that occur with formation of atherosclerotic plaques. "Studies have found that a lower ALB level was associated with an increased risk of mortality in cardiovascular disease and carotid atherosclerosis." (PMID 37153679, 2023). "Lower levels of albumin have also been associated with higher inflammation, hypercoagulation and carotid atherosclerosis in people with human immunodeficiency virus infection (HIV)." (PMID 32722020, 2020). "Additionally, lower serum albumin is associated with higher inflammation and carotid atherosclerosis in subjects with HIV under suppressive anti-retroviral therapy." (PMID 41301405, 2025). "We assume that such effects of azelnidipine leads to the reduction of urinary albumin excretion and carotid atherosclerosis." (PMID 26388951, 2015). "We assume that the reduction of inflammation by azelnidipine explains, at least in part, its beneficial effects on urinary albumin excretion and carotid atherosclerosis." (PMID 26388951, 2015). "The multivariable Cox regression analysis for cerebrovascular events included age, low-dose statin usage, NIHSS score at admission, GCS score at admission, platelet count (PLT) at admission, albumin levels at admission, carotid atherosclerosis, among other factors." (PMID 40642210, 2025). "Therefore, to explore the mechanism how azelnidipine decreased urinary albumin excretion and carotid atherosclerosis, we evaluated plasma levels of inflammatory cytokines, adipocytokines and soluble adhesion factors." (PMID 26388951, 2015). "In addition, inflammatory cytokine levels were decreased only in azelnidipine group which possibly explains such beneficial effects of azelnidipine on urinary albumin excretion and carotid atherosclerosis." (PMID 26388951, 2015). "Serum albumin may predict progression of carotid atherosclerosis independent of traditional risk factors." (PMID 30515432, 2018). "The main exposures were carotid atherosclerosis, assessed using carotid intima-media thickness (CIMT) using B-mode ultrasonography, and microalbuminuria, measured using spot urine albumin (SUA) and urine albumin-creatinine ratio (uACR)." (PMID 35471573, 2022). "Albumin is a negative acute-phase reactant and its serum concentrations are expected to decline in proinflammatory conditions such as atherosclerotic heart disease." (PMID 40667402, 2025).